BRAF (B-Raf proto-oncogene, serine/threonine kinase)
Diseases named in the same sentence as BRAF in open-access papers (continued):
Sharing a sentence is not in itself a finding about the gene and the disease.
melanoma (continued). "Trametinib is another selective and potent MEK inhibitor that has been clinically approved for BRAF mutant cancers (mainly melanoma)." (PMID 31612108, 2019). "Metastatic melanomas frequently have activating mutations in the MAPK pathway, and resistance to BRAF inhibitors was thought to result from downstream MEK activation." (PMID 30925887, 2019). "miRNA expression in two BRAF-mutant melanoma cell lines and their dabrafenib-resistant sublines was determined using Affymetrix GeneChip® miRNA 3.1 microarrays and/or qRT-PCR." (PMID 31227006, 2019). "Patients with malignant melanoma often relapse after treatment with BRAF and/or mitogen‐activated protein kinase kinase (MEK) inhibitors (MEKi) owing to development of drug resistance." (PMID 30339727, 2019). "A subset of melanomas overexpresses PGC1α, and treatment of BRAF-mutant melanomas with the BRAFi PLX4720 (a vemurafenib analogue) has been shown to upregulate PGC1α." (PMID 30971321, 2019). "The enforced expression of MITF was demonstrated to induce the differentiation and lower cell proliferation in BRAFV600E mutated melanoma cells, thereby highlighting the equivocal role of MITF in melanoma progression and BRAF inhibitor resistance." (PMID 31416288, 2019). "In this analysis BRAF, KIT, NRAS, and PIK3CA mutations were examined by next generation sequencing (NGS) in 446 melanomas in a clinical diagnostic setting." (PMID 31277584, 2019). "We first used high-throughput pharmacogenomic profiling to identify potentially repurposable compounds against BRAF-mutant melanoma brain metastases." (PMID 30971321, 2019). "Systemic response rates in melanoma patients range from 11-21%, with better response reported in patients with BRAF wild-type melanoma with PD-L1 expression." (PMID 31803366, 2019). "We have recently reported that FZR1 promotes BRAF ubiquitination and subsequent proteolysis in normal melanocytes, whereas this process is inhibited in melanoma cells due to inhibitory phosphorylations by ERK and CDK kinases at the N terminus of FZR118." (PMID 31015455, 2019). "A recent study showed that an inhibition of E2F1 leads to increased cell death in melanoma cells, even if they are resistant to BRAF-inhibitors." (PMID 31888467, 2019). "Targeting the Aurora kinases A and B with Danusertib in combination with the BRAF inhibitors Vemurafenib and Dabrafenib synergistically killed A375 melanoma cells." (PMID 30728057, 2019). "Our side-by-side comparison of efficacy and safety of dabrafenib/trametinib, vemurafenib/cobimetinib, and encorafenib/binimetinib in patients with BRAF-mutant melanoma identified important differences in efficacy, safety, and tolerability." (PMID 31653096, 2019). "Here, we show that in BRAFV600E-melanoma, autophagy is induced by BRAF inhibitor (BRAFi), as part of a transcriptional program coordinating lysosome biogenesis/function, mediated by the TFEB transcription factor." (PMID 30979895, 2019). "Altogether, we have identified an unexpected activity of TFEB-mediated autophagy–lysosomal function in regulating TGF-β signaling, which when compromised, promotes tumor progression and drug resistance in BRAF-mutant melanoma." (PMID 30979895, 2019). "After B-RAF V600 and N-RAS Q61, RAC1 P29S is the most frequent mutation found in wild-type for BRAF and N-RAS melanomas and is detected in 5–9% of all melanomas." (PMID 31248017, 2019). "In melanoma, BRAFV600E mutation accounts for 90% of all BRAF mutations, while BRAFV600K/R/D are less common." (PMID 30886831, 2019). "Encorafenib/binimetinib is a new combination BRAF/MEK inhibitor used in the treatment of advanced or metastatic BRAFV600-mutant melanoma." (PMID 31687241, 2019). "Among 82 studied patients, 12 cases (60%) of the malignant melanoma group revealed a high intensity of immunostaining for BRAF V600E, while a signifi- cant expression of this marker did not occur in the other investigated skin neoplasm." (PMID 31531096, 2019).
melanoma (continued). "We also employed DMBC22 cell line that was previously assigned to the NRAS subtype of melanoma as it harbored a homozygous NRASQ61R variant and a wild-type BRAF." (PMID 30989459, 2019). "This work culminated in the Food and Drug Administration approval of the MEK inhibitor (MEKi) trametinib for BRAF-mutant melanoma." (PMID 30353166, 2019). "Several studies, both in melanoma and in thyroid cancer, were aimed at evaluating the potential effect of BRAF-inhibitors on the secretion of chemokines." (PMID 31762942, 2019). "Regrettably, melanoma acquires resistance to BRAF inhibitors, e.g., vemurafenib (PLX4032) casting doubt on this promising melanoma targeted therapy." (PMID 30745871, 2019). "We showed that melanoma cells resistant to the BRAF inhibitor are characterized by a lower proliferation rate and they acquire a spindle-like shape." (PMID 31877948, 2019). "In a genetically engineered mouse model, conditional melanocyte-specific expression of either BRAF D594A or KRAS G12D was insufficient to induce nevi or melanomas." (PMID 31398831, 2019). "Since BRAF is the predominant driver for MAPK activation in most melanoma cells, we chose to focus on elucidating how ubiquitination of BRAF by ITCH dictates the BRAF/MEK/ERK signaling cascade in the melanoma setting." (PMID 31015455, 2019). "Vemurafenib was the first selective BRAF inhibitor that showed dramatic therapeutic responses in patients with V600 BRAF-mutant melanoma." (PMID 31514305, 2019). "Compared with the control group, a robust, antigen-specific cytotoxic T-cell response and potent tumour growth inhibition were elicited by BRAF peptide vaccine in a murine BRAF-mutant melanoma model." (PMID 31617076, 2019). "Treatment of BRAF-mutant primary melanoma cells with up to 24 h of BRAF, MEK, or ERK inhibitors induced MCL-1 dependence." (PMID 31727958, 2019). "Other research studies have reported falling levels of circulating free DNA (ctDNA) for tumor survival-promoting mutant kinase BRAF, NRAS, and KIT alleles in melanoma patients who are undergoing immunotherapy." (PMID 30941125, 2019). "For example, the common V600E mutation in the BRAF oncogene is a marker of the response to the BRAF V600E-targeting drug vemurafenib in melanoma." (PMID 30986244, 2019). "Recurring hotspot mutations in the V600 codon of BRAF or Q61 codon of NRAS are the most prevalent and occur in approximately 35–50% and 10–25% of melanomas, respectively." (PMID 30312528, 2019). "We conducted a meta‐analysis to evaluate the efficacy and safety between BRAF inhibition plus MEK inhibition combination therapy and BRAF inhibition monotherapy in melanoma patients." (PMID 31393083, 2019). "With these results, we are the first to show that long-term melanoma therapy with BRAF inhibitors can prevent further therapeutic success with dacarbazine due to acquisition of cross-resistance." (PMID 30631106, 2019). "Panniculitis and vitiligo-like lesions have been recently identified as rare cutaneous side effects of the combination of BRAF and MEK inhibitors, a standard of care in metastatic and locally advanced BRAF V600 mutated melanoma." (PMID 30939167, 2019). "We observed similar effects upon treatment with a MEK inhibitor and in three other BRAF-mutant melanoma cell lines with BRAF or MEK inhibitors." (PMID 31727958, 2019). "The overall toxicity profile was consistent with that reported in melanoma patients being treated with a BRAF inhibitor drug." (PMID 31762942, 2019). "For example, mutational activation of NRAS and MEK1/2 and increased CRAF protein level have been reported in the presence of BRAF inhibition in BRAF-mutant melanoma." (PMID 31426419, 2019). "In Phase I and II clinical trials, dabrafenib demonstrated a 53–78% partial or complete response rate in melanoma patients bearing mutant V600E BRAF." (PMID 30975211, 2019). "60% of the evaluated malignant melanoma patients expressed this mutant BRAF more commonly than populations in other reports." (PMID 31531096, 2019).
melanoma (continued). "In melanomas, some BRAF V600E‐driven tumors become resistant to the BRAF inhibitor vemurafenib through overexpression of BRAF V600E." (PMID 30422399, 2019). "In particular, in this study we retrospectively analysed advanced melanomas that had directly progressed from stage IB/II AJCC (American Joint Committee on Cancer) 2017, whose mutational status of BRAF, KRAS, NRAS and PIK3CA genes had already been tested." (PMID 30934988, 2019). "In the recent years, more specific, targeted therapies against melanoma have appeared, mostly directed against BRAF kinase." (PMID 31649529, 2019). "For OS, sex, melanoma subtype, melanoma stage, presence of brain metastasis, ulcerations and first BRAF inhibitor initiated were candidate variables." (PMID 30899440, 2019). "Our data presented herein demonstrate that CDK11 is highly expressed in both BRAF- and NRAS-mutated melanoma cell lines." (PMID 30987032, 2019). "Although at lower prevalence, the development of other tumors, including de novo melanomas, genital and oral mucosal squamo-cellular cancers and basal-cell carcinoma in patients treated with BRAF inhibitors was also reported." (PMID 31762942, 2019). "The development of a targeted therapy against this constitutively active BRAF has revolutionized the treatment of late-stage melanoma patients." (PMID 30728057, 2019). "To this purpose, we tested our therapy in a model system of BRAF V600E mutant melanoma, using the A375 xenograft model." (PMID 31468706, 2019). "Concomitant treatment with the MCL-1 inhibitor and BRAF inhibitor had modest synergy in A375M melanoma cells." (PMID 31727958, 2019). "To date, Dabrafenib and Vemurafenib are FDA-approved for BRAF V600E-positive malignant melanomas, but clinical trials of phase 1–2 were currently performed." (PMID 31357735, 2019). "Through the emergence of a drug-tolerant, dedifferentiated, slow-cycling cell subpopulation, BRAF-mutant melanomas treated with MAPK inhibitors adapt to drug over time." (PMID 31581557, 2019). "Inhibitors of MAPK signaling, such as BRAF and MEK inhibitors, are used to treat BRAF mutated melanoma and can alter the melanoma immune landscape leading to increased T cell infiltration." (PMID 30899263, 2019). "In BRAF-mutant melanoma brain metastasis, we show that β-sitosterol efficiently prevented resistance to BRAFi therapy in vivo." (PMID 30971321, 2019). "This outcome further reaffirms that Indonesian melanoma cases do have a significantly lower BRAF V600 prevalence compared to Asia in general." (PMID 31890008, 2019). "Here, we report a case of a 45 year-old Caucasian lady with BRAF-V600E mutant metastatic melanoma to the brain who had whole brain radiotherapy followed by two Gamma knife radiosurgery treatments for localized disease progression." (PMID 30972290, 2019). "It was demonstrated that wild-type melanoma cell lines were more responsive to FGF2 than BRAF mutant or NRAS mutant cell lines." (PMID 31167513, 2019). "BRAF and NRAS-mutated melanomas showed a significantly lower incidence of coexisting mutations of different genes (10 and 8.1%, respectively) as compared to PIK3CA, HRAS and KIT-mutated melanomas (75, 67 and 36%; all P < .001)." (PMID 31277584, 2019). "On the other hand, most patients with mutant BRAF melanoma develop drug resistance during their therapy." (PMID 31284513, 2019). "Despite the fact that BRAF inhibitors have a high response rate in BRAF V600 mutant melanoma, and non-small cell lung cancer, their efficacy as monotherapy in BRAF V600E CRC is limited." (PMID 30736475, 2019). "The U.S. Food and Drug Administration (FDA) has approved trametinib (GSK1120212) for treatment of BRAF-mutant metastatic melanoma, and a phase III clinical trial using trametinib in melanomas with BRAFV600E or BRAFV600K mutations showed promising responses." (PMID 31470659, 2019).
melanoma (continued). "We found that the vemurafenib + tretinoin combination treatment suppressed gene expression of the majority of BRAF melanoma network genes that were highly up-regulated in patient tumors." (PMID 30820351, 2019). "To understand CDK11 function in melanoma, we evaluated protein and RNA levels of CDK11, Cyclin L1 and Cyclin L2 in benign melanocytes and BRAF- as well as NRAS-mutant melanoma cell lines." (PMID 30987032, 2019). "By contrast, the selective knocking down of ERK1 or ERK2 in another study killed melanoma cells and enhanced the action of the BRAF Inhibitor." (PMID 31126017, 2019). "We confirmed the development of BRAFi resistance in our BRAFi‐treated melanoma cell lines by demonstrating reduced sensitivity to BRAF inhibitors, increased ERK1/2 activity and increased WNT5A expression." (PMID 30582770, 2019). "The aim of this study was to evaluate the prognostic value of plasma lncRNAs in BRAF-mutant advanced melanoma patients treated with a BRAF inhibitor." (PMID 31231466, 2019). "Targeted therapy has been limited to BRAF mutant melanoma, and even dual MEK/BRAF blockade leads to efficacy only for short periods of time, likely due to activation of alternative signaling pathways." (PMID 30824801, 2019). "Another mTOR inhibitor, temsirolimus, in combination with chemotherapeutic agent temozolomide, exhibited significant decrease in tumor growth and increased apoptotic death in melanoma cells that showed resistance to BRAF inhibitor vemurafenib." (PMID 31370278, 2019). "In BRAF-inhibitors-treated patients who develop drug resistance, the decreased expression of melanoma’s antigens and the reduced number of infiltrating CD8 T-cell parallels the patients’ clinical progression." (PMID 31762942, 2019). "During melanoma development, BRAF induces expression of MITF in order to control tumour growth, but this regulation is inverted when BRAF is inhibited." (PMID 30277012, 2019). "Real‐world overall survival of patients with advanced BRAF mutant melanoma treated with front‐line BRAF/MEK inhibitors, anti‐PD‐1 antibodies, or nivolumab/ipilimumab." (PMID 31677253, 2019). "The CAP alone has higher BRAF activity as compared to the SN group, but the co-treated group showed significantly reduced BRAF levels which signify a reduction in melanoma." (PMID 31126298, 2019). "In melanoma and papillary thyroid carcinoma, ERK activated by mutated BRAF induces direct phosphorylation of ETS1 or phosphorylation of another transcription factor FOS followed by GABPB transcriptional activation." (PMID 30709063, 2019). "Both in clinical samples and experimental models, BRAF inhibitor resistant melanoma cells expressed higher levels of both intra- and extracellular NAMPT than their sensitive counterparts." (PMID 32010616, 2019). "Many targeted cancer treatments have now emerged that focus on tumour specific drivers (e.g., BRAF inhibitors to combat mutant BRAF-dependent melanomas and antibody-based therapies to address over-expression or aberrant EGFR signaling)." (PMID 31500184, 2019). "In BRAF inhibitor-resistant melanoma cells, inhibition of actin polymerisation and actomyosin contractility was found to suppress both YAP/TAZ activity and drug-resistance, thus highlighting an important role of the actin cytoskeleton in this context." (PMID 31058846, 2019). "BRAF and RAS are the most frequently mutated mitogen-activated protein kinase (MAPK) genes in melanoma." (PMID 30956763, 2019). "Studies proved that the number of tumor-associated macrophages increases in BRAF- and MEK-depleted melanoma cells and BRAF (V600E) melanoma allografts." (PMID 31652660, 2019). "There have been significant advancements in the adjuvant therapy of melanoma with the use of checkpoint inhibitors and targeted therapies for BRAF mutant melanomas." (PMID 30725205, 2019).
melanoma (continued). "Three BRAFi/MEKi combinations (dabrafenib/trametinib, vemurafenib/ cobimetinib, and encorafenib/binimetinib) are considered the standard treatments for patients with advanced BRAF-mutant melanoma." (PMID 31653096, 2019). "Activation of the PI3K/Akt pathway has been implicated in resistance to both MEK inhibitor treatment in gastric cancer cells and BRAF/MEK inhibitor combination treatment in melanoma cells." (PMID 31769426, 2019). "CDK 4/6 inhibitors are currently being evaluated in combinations with BRAF and MEK inhibitors against BRAF- and NRAS-mutated melanomas." (PMID 31573152, 2019). "Follow-up analysis evaluated how CDK11 loss alters cell cycle function in BRAF- and NRAS-mutant melanoma cells." (PMID 30987032, 2019). "PTEN regulates the phosphotidylinositol-3-kinase (PI3K) pathway, which is a well-studied oncogenic pathway in multiple cancer types These observations have invigorated PI3K and BRAF dual inhibition strategies in patients with PTEN null melanoma." (PMID 31426419, 2019). "Resistance to BRAF inhibitors was demonstrated in an autochthonous mouse model of melanoma and was associated, in the tumor microenvironment, with the restoration of MDSC, which, previously, had been reduced by treatment with BRAF inhibitors." (PMID 31762942, 2019). "In contrast to the initial response rates (>50%) of BRAF inhibitor monotherapy in BRAFV600-mutant melanoma, approximately 5% of patients with BRAFV600E colorectal cancer respond." (PMID 30792807, 2019). "In summary, our results demonstrate that targeting melanoma’s MCL1 bias unleashes the potential of BRAF and ERK1/2 pathway inhibitors by transforming cytostatic responses into striking apoptotic cell death." (PMID 31727888, 2019). "For instance, in melanoma patients, increased secretion of HGF from surrounding stromal cells increases MET pathway signaling in melanoma cells, resulting in resilience against BRAF targeted inhibitors." (PMID 31815659, 2019). "While in patients dual treatment yielded a 64% response rate and a median PFS of 10.9 months in BRAF V600 mutation-positive NSCLC, combined RAF/MEK treatment in the class I BRAF-mutant melanoma cell line (WM793) displayed additive to antagonistic effects." (PMID 31533235, 2019). "For the first time to our best knowledge, we demonstrated that the BRAF inhibitor Dabrafenib and the MEK inhibitor Trametinib down-regulate TF in BRAFv600e mutated melanoma cells with a consequent inhibition of the coagulation cascade." (PMID 31467489, 2019). "This study shows that the pro-survival pool is biased towards MCL1 in melanoma so that BRAF or MEK1/2 inhibitors are synthetic lethal with the MCL1 inhibitor AZD5991, improving tumour growth inhibition." (PMID 31727888, 2019). "CCND1 amplification is noted in 15–20% of BRAF-mutant melanomas and can contribute to therapy resistance." (PMID 31426419, 2019). "Treating the melanoma cells with combination of BRAF inhibitor Vemurafenib and c-MET inhibitor AMG 337 or siRNA exhibited therapeutic benefits in BRAF mutant malignant melanoma." (PMID 31370278, 2019). "The results show a strong phosphorylation of ErbB3 in melanoma cells upon treatment with CM from BRAF inhibitor-exposed melanoma cells, similar to what happens after direct cell exposure to the same BRAF inhibitor." (PMID 31557826, 2019). "Targeted oncotherapy is one of the standard treatment for progressive stage 4 melanoma, and BRAF inhibitors (e.g. vemurafenib, dabrafenib) combined with MEK inhibitor (e.g. trametinib) can effectively counter BRAFV600E-mutated melanomas." (PMID 30900145, 2019). "Mutant BRAF is an important driver in melanoma development, occurring in about 50% of cutaneous melanomas." (PMID 31752344, 2019). "To compare our BRAF/NRAS ctDNA findings with a more established marker for disease progression in melanoma we evaluated the levels of LDH in serum (n = 2–21 time-points per patient)." (PMID 31767937, 2019).